GET1-SH3BGR (GET1-SH3BGR readthrough)
Synonyms: WRB-SH3BGR
Gene: Protein-coding gene on chromosome 21 (39,380,332 to 39,515,506, forward strand). Ensembl gene ENSG00000285815.
Genetic constraint (gnomAD): Loss-of-function variants: 25 observed, 27.7 expected, observed/expected ratio (o/e) 0.9, 90% interval 0.66 to 1.26. The upper end of that interval is the gene's LOEUF score, 1.26, which puts it in group 5 of 6, group 1 being the genes least tolerant of losing a copy. Missense variants: 239 observed, 264.93 expected, observed/expected ratio (o/e) 0.9, 90% interval 0.81 to 1. Synonymous variants: 98 observed, 97.14 expected, observed/expected ratio (o/e) 1.01, 90% interval 0.86 to 1.19.